ANO1 (anoctamin 1)
Diseases named in the same sentence as ANO1 in open-access papers (continued):
Sharing a sentence is not in itself a finding about the gene and the disease.
tumor (continued). "Given that tumour site exerts an important influence on the prognosis of HNSCC patients, the impact of ANO1 expression on disease course was also examined separately in each anatomic site." (PMID 26498851, 2015). "Because of the contribution of ANO1 to metastatic progression in HNSCC, poor survival, or tumor malignancy in HNSCC patients is correlated with the presence of ANO113." (PMID 24639373, 2014). "In order to analyze the distribution of the Ano1 protein expression in tumors other than HNSCC, we applied Ano1 immunohistochemistry to a multi tumor TMA composed of 3417 tissue samples (including 315 normal controls) of 80 different tumor types." (PMID 22912841, 2012). "The present report provides, for the first time, a detailed analysis of Ano1-protein expression in HNSCC and 80 different tumor types, as well as 76 types of normal tissues." (PMID 22912841, 2012). "ANO1 inhibits ferroptosis in tumor cells via phosphatidylinositol‐3‐kinase (PI3K)–Akt signaling and activates CAFs through TGF‐β release, while suppressing CD8+ T cell cytotoxicity, thereby exacerbating tumor progression." (PMID 41164803, 2025). "Studies have shown that ANO1 overexpression in HNSCC activates the mitogen-activated protein kinase (MAPK)/extracellular signal-regulated kinase (ERK) signaling pathway, promoting tumor proliferation and correlating with poor prognosis." (PMID 40356890, 2025). "ANO1 plays a pivotal role in the pathophysiological processes of both non-neoplastic and neoplastic diseases and represents a promising therapeutic target for disease intervention." (PMID 40356890, 2025). "In conclusion, ANO1 is critically involved in the pathogenesis of both tumor and non-tumor diseases, particularly in facilitating tumor invasion and metastasis." (PMID 40356890, 2025). "Anoctamin-1 (ANO1), a crucial component of calcium-activated chloride channels (CaCCs), is expressed widely in various cell types, including epithelial cells, vascular smooth muscle cells, and tumour cells, and influences cell proliferation and migration." (PMID 40396170, 2025). "Strategies targeting ANO1, such as small molecule modulators or gene-silencing techniques, have shown preclinical promise in both non-neoplastic and neoplastic diseases." (PMID 40356890, 2025). "In pancreatic cancer, ANO1 influences the TME through cytokine and interleukin signaling, promoting fibroblast accumulation and reducing CD8+ T cell infiltration via paracrine signaling, thereby creating a TME that facilitates tumor growth and immune evasion." (PMID 40356890, 2025). "Transcriptionally, ANO1's expression was higher in GC/EC/CRC tumor than in normal tissue, while ANO1‐amplified patients displayed higher ANO1 expression than nonamplified patients according to TCGA datasets." (PMID 37341301, 2023). "The percentage of ANO1 positive tumor cells was scored on the 0–3 scale as follows: 0 (absence of positive cells), 1 (less than 33% positive cells), 2 (33–66% positive cells), and 3 (more than 66% positive cells)." (PMID 31266974, 2019). "The expression of ANO1 was not restricted to the cytoplasmic membrane, but was expressed in both the cytoplasm and nuclei of tumor cells." (PMID 29416639, 2018). "Based on the literature and our previous findings, we hypothesized that suppression of ANO1 results in enhancement of caspase upstream pathways such as TNF-α signaling, subsequently leading to inhibition of tumor proliferation and metastasis." (PMID 29899325, 2018). "So, the tumours contained both fused and wild type genes and transcripts, since wild type genes (ANO1 and PLA2G16) were amplified by PCR (data not shown) from DNA of the sample but no PCR product was observed for the fused gene using proper primers." (PMID 28886030, 2017). "Similar to our in vitro data, inhibition of ANO1 reduced tumour growth in KPH2 but not KP allografts." (PMID 26837714, 2016). "The role of ANO1 in promoting cell proliferation seems to be not confined in the tumor microenvironment." (PMID 26811235, 2016).
tumor (continued). "In addition, ANO1 knockdown abrogated cell proliferation in vitro and tumor growth of HNSCC tumor xenografts, which parallels with the cell cycle arrest at G1/S phase transition." (PMID 26811235, 2016). "The qRT-PCR does not confer visualization of ANO1, so one can argue that tumor cells have just been detected indirectly." (PMID 27153560, 2016). "In turn, ANO1 overexpression coincided with elevated CAMKII and mTORC1 signalling in these tumours." (PMID 26837714, 2016). "All tumours showing ANO1-positive expression harboured ANO1 gene amplification; however, gene amplification did not lead to increased expression in all cases." (PMID 26498851, 2015). "In summary, our data demonstrate that degradation of ANO1 rather than inhibition of ANO1 channel activity is critical for the inhibition of ANO1-dependent cell proliferation in ANO1-amplified tumor cells." (PMID 24599954, 2014). "PGG is known to inhibit cell proliferation in tumor types that do not express ANO1, so its cytotoxic effect in tumor cells is not due to ANO1 inhibition." (PMID 24599954, 2014). "Multivariate analysis including tumor stage (pT) and tumor location (both significant in univariate analysis) revealed Ano1 positivity (p = 0.022), but not Ano1 gene amplification (p = 0.382) as independent prognostic factor besides pT stage (p = 0.0003)." (PMID 22912841, 2012). "Additionally, elevated ANO1 expression is accompanied by increased phosphorylation of ERK1/2, activating the MAPK/ERK pathway while upregulating Cyclin D1 expression, thereby facilitating the G1/S phase transition and promoting tumor cell proliferation." (PMID 40356890, 2025). "ANO1, a key CaCC, plays a critical role in both non-neoplastic and neoplastic diseases." (PMID 40356890, 2025). "Our study found that ANO1 expression positively correlated with FAP-positive CAFs and negatively correlated with CD8-positive TILs, suggesting that ANO1 may be a key regulator of the tumor immune microenvironment." (PMID 38352864, 2024). "Also, CAI/BBR selectively showed anti‐tumor effectiveness in an ANO1‐positive GC PDX rather than in an ANO1‐negative GC PDX, and were both valid to inhibit the growth of a GIST PDX model with medium ANO1 positivity." (PMID 37341301, 2023). "Furthermore, we suggest that the dynamic change of ANO1, TMEM38B, TMEM158, and TMEM45A may indicate stellate cell activation and trigger tumor stromal remodeling." (PMID 37265785, 2023). "ROC curves showed that the expression level of Ano1 was discriminated by PR (P=0.040), TNBC (P=0.051), and tamoxifen treatment (P=0.017), and the expression level of Ki67 was discriminated by tumor size (P=0.028), clinical stages (P=0.004), and HER2 status (P=0.003)." (PMID 29156699, 2017). "We further analyzed the expression of the Ano1 protein in more than 4′000 human samples from 80 different tumor types and 76 normal tissue types and detected that besides HNSCC and GISTs, Ano1 was rarely expressed in other tumor samples or healthy human tissues." (PMID 22912841, 2012). "The relationship between ANO1 and tumourigenesis has not been explained clearly, but a secretory environment might be important for tumour-cell proliferation." (PMID 22102040, 2011). "Based on the literature reports and our previous findings, we therefore hypothesized that suppression of ANO1 overexpression may result in an upregulation of death receptor-ligand systems such as TNF-α signaling mediated by FADD, thus leading to suppression of tumor proliferation and metastasis." (PMID 29899325, 2018). "Furthermore, ANO1 is not amplified and overexpressed in tumours that express HPV E6 and E7." (PMID 20664600, 2010).
cancer (194 papers, 2010 to 2026). A tumor composed of atypical neoplastic, often pleomorphic cells that invade other tissues. "Anoctamin 1 (ANO1), a calcium-activated chloride channel, has been implicated in cancer progression and is an emerging therapeutic target." (PMID 40520165, 2025). "Since the pharmacological inhibition of ANO1 in various cancer cell types reportedly causes apoptosis, we evaluated the apoptotic effects of vitexicarpin in HT29 and PC9 cells." (PMID 40520165, 2025). "A recently identified calcium‐activated chloride channel protein, anoctamin 1 (ANO1), is proposed to have a fundamental role in proliferation of cells and tumorigenesis in most prevailing type of cancers that further linked with death in men." (PMID 39830909, 2025). "As the pharmacological inhibition of ANO1 in various cancer cell types has been reported to cause apoptosis, we evaluated the apoptotic effects of vitekwangin B in PC3 and PC9 cells." (PMID 38659592, 2024). "This high expression of ANO1 protein is associated with poor prognostic survival in cancer patients." (PMID 38892219, 2024). "Anoctamin 1 (ANO1) promoted TGF-β secretion by gastrointestinal (GI) cancer cells, which attracted cancer-associated fibroblasts (CAFs) into the TME by blocking ferroptosis in a PI3K/Akt signaling-dependent manner." (PMID 38283351, 2023). "ANO1 was found to be a risk factor in many cancer types (HR = 1.52, 95% CI: 1.19-1.92), and was suggested to be a prognostic factor." (PMID 36712866, 2022). "The ANO1 gene resides within the chromosome 11q13 region, which is frequently amplified in human cancers, and is associated with a poor prognosis." (PMID 34769467, 2021). "ANO1 gene is located within the chromosome 11q13 that is one of the most frequently amplified regions in human cancer and associated with poor prognosis." (PMID 29899325, 2018). "ANO1 gene is located within the 11q13 amplicon, one of the most frequently amplified chromosomal regions in human cancers that is associated with a poor prognosis." (PMID 27732935, 2016). "The ANO1/TMEM16A gene is localized on 11q13, one of the most frequently amplified regions in human cancers and associated with a poor prognosis." (PMID 26305547, 2015). "This study provides original evidence demonstrating the potential utility of ANO1 gene amplification as a cancer risk marker in patients with laryngeal dysplasia, and also that the prognostic significance of ANO1 expression in HNSCC seems to be site-dependent." (PMID 26498851, 2015). "The CaCC ANO1/TMEM16A gene is located in chromosome band 11q13 that is one of the most frequently amplified regions in human cancer and is associated with a poor prognosis." (PMID 26305547, 2015). "Overall, it seems that ANO1 overexpression produced different effects on the proliferation of different cancer cell lines, implying that the underlying process is complicated." (PMID 24639373, 2014). "Overexpression of ANO1 in gastrointestinal cancer cells inhibits ferroptosis of tumor cells, promotes the recruitment of cancer‐associated fibroblasts (CAFs) by cancer cells, confers resistance to immunotherapy, and thereby affects the therapeutic effect of cancer treatment." (PMID 41152153, 2025). "In addition, the increased expression of ANO1 is known to be associated with poor prognosis in cancer patients." (PMID 36674697, 2023). "Thus, despite insignificant statistics caused by limited sample size, ANO1 amplification/upregulation retrospectively indicated adverse immunotherapeutic outcomes in multiple cancer types." (PMID 37341301, 2023). "Since PI3K‐Akt is one of the most frequently mutated and activated signaling in human cancers, whether ANO1 would ignite other pathways downstream of PI3K‐Akt signaling deserved further exploration." (PMID 37341301, 2023). "It is only known that ANO1 was linked with cancer metastasis, but the molecular basis of this process remains unknown." (PMID 34638224, 2021).
cancer (continued). "Pharmacological inhibition of the ANO1 protein causes apoptosis in various cancer cells." (PMID 32899792, 2020). "Collectively, these results suggest that ANO1 might be an inducer of EMT that is associated with invasiveness of cancer cells and/or involved in resistance to the initial therapies." (PMID 29416639, 2018). "Signaling pathways which may be involved in the progression of human cancers in association with ANO1 include the MAPK signaling, cell cycle regulation pathway, the EGFR pathway, and epithelial-mesenchymal transition (EMT)." (PMID 29416639, 2018). "The cell-specific mechanism underlying regulation of cell proliferation by Ano1 remains unclear, and may be associated with activation of different signaling pathways by Ano1 in different cancer cells." (PMID 29156699, 2017). "Ano1 has been implicated in many diseases such as cancer, hypertension, and cystic fibrosis." (PMID 29156699, 2017). "Our data have also shown that Ano6-KD significantly attenuates ERK phosphorylation, which is implicated in the regulation of cancer cell proliferation by Ano1, suggesting that Ano6 is potentially involved in regulating myoblast proliferation through the ERK signaling pathway." (PMID 24663380, 2014). "More recently, ANO1-mediated PI3K-AKT activation has been shown to impair ferroptosis in gastrointestinal cancers while simultaneously remodeling the tumor microenvironment through recruitment of cancer-associated fibroblasts (CAFs) and suppression of CD8+ T-cell activity." (PMID 41155636, 2025). "Additionally, ANO1 has been associated with apoptosis in a variety of cancers." (PMID 38685684, 2024). "ANO1 is another calcium-activated chloride channel that plays a central role in the proliferation, invasiveness, and apoptosis of various malignant tumors." (PMID 41601884, 2026). "It is anticipated that integrating ANO1 in combination cancer therapy is a promising direction to improve therapeutic efficacy." (PMID 40396170, 2025). "Anoctamin 1 (ANO1), also known as transmembrane protein 16A (TMEM16A), is a calcium-activated chloride channel that has been implicated in tumorigenesis and cancer progression." (PMID 40520165, 2025). "The goal of this work is to offer new perspectives for further study on the role of ANO1 in gastrointestinal cancers and to support improvements in therapeutic strategies for cancer diagnosis and treatment through the targeting of ANO1." (PMID 40396170, 2025). "Natural compounds such as schisandrathera D and vitekwangin B reduce cell viability and induce apoptosis in cancers, such as prostate cancer, by downregulating ANO1 protein expression." (PMID 41155636, 2025). "Vitexicarpin significantly inhibited ANO1 function and protein levels, reduced cancer cell viability, and induced apoptosis." (PMID 40520165, 2025). "ANO1, a member of the transmembrane protein 16 (TMEM16) family, also known as TMEM16A, was initially identified as a Ca2+-activated chloride channel and has been reported to be highly expressed in various cancer types." (PMID 40707002, 2025). "With the evolution of technology and research, the role of ANO1 in cancer is likely to be profound and promising." (PMID 40396170, 2025). "Due to its significant functions in cancer, ANO1 is recognized as a potential clinical therapeutic target." (PMID 40396170, 2025). "Vitexicarpin inhibited ANO1 channel function, reduced ANO1 protein levels, decreased cancer cell viability, and induced apoptosis in CRC and NSCLC cell lines." (PMID 40520165, 2025). "Another CaCC, Bestrophin-1, has also been implicated in cancer progression, particularly in CRC and oral squamous carcinoma, potentially through modulation of calcium signalling and functional interaction with ANO1." (PMID 40806720, 2025). "An increasing number of studies have characterized ANO1 as a chloride channel whose molecular expression significantly impacts cancer at various stages." (PMID 40396170, 2025).
cancer (continued). "Clinically used drugs inhibit cancer cells by downregulating ANO1, with promising safety and economic efficacy." (PMID 40396170, 2025). "It reduced ANO1 protein expression by promoting proteasomal turnover of ANO1 in parental cancer cells." (PMID 40396170, 2025). "Inhibiting ANO1 not only reduces cell viability but also impairs cell migration and proliferation across multiple cancer types." (PMID 40520165, 2025). "ANO1, a calcium-activated chloride channel (CaCC), plays a role in key physiological functions and is frequently overexpressed in various cancers, including CRC." (PMID 39941737, 2025). "Overall, ANO1 has emerged as a crucial therapeutic target with great potential in cancer treatment and various disease interventions." (PMID 40356890, 2025). "ANO1, also known as TMEM16A, functions as a calcium-activated chloride channel and is implicated in various malignant tumors, influencing their progression, metastasis, proliferation, and ability to resist apoptosis." (PMID 38562143, 2024). "The stable transfection of ANO1 shRNA efficiently silenced the expression of ANO1 expression in the cancer cells." (PMID 38773164, 2024). "Consistent with expectations from these results, our in vivo data underscore the role of ANO1 in increasing metastatic gene expression, cancer cell bone relocation, and osteoclastic bone lysis." (PMID 38773164, 2024). "After cancer cells were treated with 1 μM vitekwangin B, ANO1 protein levels were significantly decreased in PC3 and PC9 cells." (PMID 38659592, 2024). "Numerous in vitro and in vivo studies have shown that pharmacological downregulation of ANO1 significantly inhibits cancer cell proliferation, growth, and migration." (PMID 38659592, 2024). "While ANO1 plays multifaceted roles in various physiological processes, such as chloride ion secretion and cancer development, its chemotherapeutic potential is realized through the inhibition of its function and reduction of its protein expression." (PMID 38659592, 2024). "Although the underlying mechanism is still unclear, inhibition and downregulation of ANO1 have been shown to inhibit cell migration, proliferation, and invasion in cancer cells highly expressing ANO1." (PMID 38892219, 2024). "Anoctamin 3 (ANO3) was another downregulated genes whose paralogue ANO1 is a known cancer marker for head and neck squamous carcinoma." (PMID 38038766, 2024). "ANO1 has been suggested as a therapeutic target for various cancers since it is highly amplified or overexpressed in various types of cancer and pharmacological inhibition or downregulation of ANO1 shows anticancer activities." (PMID 36674697, 2023). "We also noticed that through restoring inhibited ferroptosis, ANO1 knockdown repressed cancer cells’ expression/secretion of TGF‐β and the recruitment of CAFs." (PMID 37341301, 2023). "Inhibition of ANO1 activity or downregulation of ANO1 expression in these cancer cells is known to exhibit anticancer effects." (PMID 36674697, 2023). "Considering ANO1's critical role in regulating cancer progression and immune escape, we recommend it both as a feasible biomarker for immunotherapy and a promising target for future therapies." (PMID 37341301, 2023). "In recent studies, ANO1 has been proposed as a potential therapeutic target for several cancers, including OSCC." (PMID 37274097, 2023). "Taken together, ANO1 exerts its role in facilitating cancer progression and repressing immunotherapeutic responses through inhibiting cancer ferroptosis." (PMID 37341301, 2023). "ANO1 was a cancer biomarker prior to it is identification as a chloride channel in GIST known as DOG1, and it has received several other names including ORAOV2, and TAOS-2 among oncologists." (PMID 36836529, 2023). "Even though the underlying mechanism is not clear, inhibition of ANO1 activity and downregulation of ANO1 expression show anticancer effects by inhibiting cell proliferation, migration, and invasion and inducing apoptosis in various cancers." (PMID 36674697, 2023).